LINC00892 (long independently transcribed non-coding RNA 892)
Gene: Long non-coding RNA gene on chromosome X (136,639,531 to 136,642,546, forward strand). Ensembl gene ENSG00000233093.
Diseases named in the same sentence as LINC00892 in open-access papers:
LINC00892 is named in the same sentence as 4 diseases in open-access papers, as found by Europe PMC text mining. Sharing a sentence is not in itself a finding about the gene and the disease. The quoted sentences say what the papers report.
bladder cancer (2 papers, 2023 to 2025). "LINC00892 involved in molecular subtype and risk model may be useful in improving the prognostic prediction of bladder cancer patients with different clinical situations and may help to find a useful target for tumor therapy." (PMID 36739404, 2023). "For instance, LINC00892 has been reported to be a predictor of prognosis and immunotherapeutic response in bladder cancer." (PMID 40308809, 2025).
tumor (2 papers, 2023 to 2025). "In vivo, LINC00892 overexpression suppressed tumor growth and metastasis in a xenograft mouse model, further supporting its tumor-suppressive function." (PMID 40308809, 2025).
cancer (1 paper, 2021). A tumor composed of atypical neoplastic, often pleomorphic cells that invade other tissues. "Despite several kinds of research that have illuminated the role of LINC00892 and LINC00996 in multiple cancers, their function in NSCLC has not been studied and deserves further investigation considering its significant prognostic value in NSCLC." (PMID 34861872, 2021).
LINC00892 also shares sentences with these, for which no sentence is quoted: Graves disease (1 paper).